FGFR3 (fibroblast growth factor receptor 3)
Diseases named in the same sentence as FGFR3 in open-access papers (continued):
Sharing a sentence is not in itself a finding about the gene and the disease.
tumor (continued). "Noticeably, establishment of single clones overexpressing FGFR3-IIIc in Capan-2 cells showed that tumor growth inhibition was dependent on FGFR3-IIIc expression levels (R2 about 0.87)." (PMID 23902722, 2013). "Very interestingly, overexpression of both FGFR3-IIIb and –IIIc inhibited Capan-2 and BxPC-3 tumor growth (about 2-fold decrease)." (PMID 23902722, 2013). "In light of this data, it appeared that in epithelial-like pancreatic cells (BxPC-3 and Capan-2), FGFR3 had tumor suppressive effects, while in cells with mesenchymal cell features (Mia PaCa-2 and PANC-1), FGFR3 had oncogenic effects." (PMID 23902722, 2013). "In vivo tumor formation confirmed the in vitro data since overexpression of both FGFR3-IIIb and –IIIc strongly promoted PANC-1 (2-3-fold increase) and even more the Mia PaCa-2 (13-17-fold increase) tumor growth." (PMID 23902722, 2013). "In tumors from epithelial origin, FGFR3 signal can limit tumor growth, explaining why the 4p16.3 locus bearing FGFR3 is frequently lost and why activating mutations of FGFR3 in benign or low grade tumors of epithelial origin are associated with good prognosis." (PMID 23902722, 2013). "Although our results indicate that FGFR1 plays a less important role than FGFR3 in driving BC tumor cell proliferation, they also strongly suggest that FGFR1 plays crucial roles in invasion and metastasis." (PMID 23468956, 2013). "FGFR3 behaved as a tumor suppressor in pancreatic cells, which was contradictory with its proposed oncogenic properties described in the literature." (PMID 23902722, 2013). "Despite contradictory results in different tumor types and models, to date, FGFR3 pathway is considered to be oncogenic in human tumors, by contrast to the situation in normal development of the long bones." (PMID 23902722, 2013). "Of FGF receptors, only FGFR3 was found with significantly enhanced expression in tumor tissues (8.21-fold, vs arachnoidal tissue)." (PMID 23285163, 2012). "Overexpression of FGFR3 was also detected in around 40% of wild-type tumours, and this was more common in invasive cases." (PMID 22899908, 2012). "A small study including 53 pTaG1-2 tumours showed that wild-type FGFR3 is predictive of disease recurrence." (PMID 22899908, 2012). "FGFR3 which is an oncogene is highly expressed in tumour samples compared to control tissue samples." (PMID 22276047, 2011). "Expression of FGFR3 isoforms IIIb and IIIc was determined for a larger number of tumour specimens (n=57) using isoform-specific real-time RT–PCR assays." (PMID 20234367, 2010).
tumor (continued). "Total RNA was isolated from normal and tumour-derived tissues (N=22) and expression of FGFR3 mRNA was measured by quantitative real-time RT–PCR relative to GAPDH." (PMID 20234367, 2010). "Tumour growth was significantly retarded by FGFR3 blockade as compared with GFPv-infected controls and uninfected cells (data not shown)." (PMID 20234367, 2010). "We earlier observed that some recurrences were wild-type when the primary tumor was mutant for FGFR3." (PMID 21072204, 2010). "For the genes WT1, GATA2, and FGFR3, the expression pattern in surgically dissected tumor tissue was consistent with that in the microdissected epithelial cells." (PMID 20426842, 2010). "As in vitro growth assays strongly indicated an anti-tumourigenic effect of FGFR3 blockade, tumour growth was assessed in vivo by injection of KD3-IIIcv- and GFPv-transduced SW480 cells into SCID mice." (PMID 20234367, 2010). "Surprisingly, 2 out of 6 of only single FGFR3+ KYM-1 cell inoculated mice also exhibited tumour formation." (PMID 19888223, 2009). "Immunohistochemical examination revealed that tumours formed by FGFR3+ KYM-1 cell contained both FGFR3+ cells and FGFR3− cells in vivo." (PMID 19888223, 2009). "In summary, we have described alternative splicing of FGFR3 in the third Ig-like loop of the extracellular domain to generate a novel spliced variant of FGFR3IIIc, FGFR3IIIS, frequently expressed in tumour but rarely in normal cells." (PMID 14520460, 2003). "Notably, the anti‐FGFR3 antibody alone exhibited negligible inhibition of tumor growth, confirming that the cytotoxic payload A2 is the core effector molecule responsible for LZU‐WZLYCS01's antitumor activity." (PMID 41168906, 2026). "Treatment with the FGFR inhibitor BGJ398 reduced tumor growth and decreased stromal FGFR3-positive components, suggesting that stromal FGFR3 may represent a potential microenvironmental vulnerability in CRC with peritoneal dissemination." (PMID 42032842, 2026). "We then assessed the relationships between genomic subtypes and clinical characteristics and found that genomic subtypes were significantly associated with T stage, tumor grade, and EORTC scores, with a gradual escalation observed among the FGFR3/HRAS, FGFR3 & chr9Del, GI, and AA-like subtypes." (PMID 40247187, 2025). "Activating FGFR3 mutations are common in non-muscle-invasive bladder cancer and are typically associated with a distinct, less aggressive tumor biology." (PMID 41019978, 2025). "Furthermore, our findings demonstrate that FGFR3 hypomethylation leading to increased FGFR3 protein expression in tumor cells is a distinctive molecular characteristic of CN." (PMID 40498174, 2025). "Furthermore, higher levels of FGFR2 and FGFR3 expression were associated with worse survival of PDAC patients and negatively correlated with tumor differentiation." (PMID 41467942, 2025). "Nevertheless, a recent study about the role of common immune-related genes and tumor microenvironment (TME) on BCG response, showed the relation between FGFR3 overexpression/mutations and a “cold” TME to be associated with BCG resistance and recurrence, which is in contrast with our findings." (PMID 40109859, 2025). "Conversely, FGFR3 is highly expressed in invasive GBM cells, suggesting a role in tumour invasion, although the underlying mechanisms remain unclear." (PMID 40467542, 2025).
tumor (continued). "Additionally, clinical observations and our own data indicate that high levels of FGFR2 and FGFR3 correlate with advanced tumor stages and poor prognosis." (PMID 41467942, 2025). "Indeed, anti-FGFR3 monotherapy produces a stronger response initially due to its direct effect on tumor fitness and its faster pharmacokinetics." (PMID 38515743, 2024). "There may be a role for future studies evaluating the dual inhibition of ERBB3 and FGFR3 simultaneously as this may be a mechanism of tumor resistance to FGFR inhibitors." (PMID 38675715, 2024). "FGFR3 alterations were found in 19% overall, 30% with upper tract, 13% with bladder and 9% with unknown tumor site." (PMID 38675715, 2024). "In various FGFR3-activated tumor models, the diminished antitumor effectiveness due to targeted FGFR3 therapy could be counterbalanced by combining it with anti-PD-1 immunotherapy, thus significantly reducing tumor growth." (PMID 38638430, 2024). "Mutations in the FGFR3 gene are associated with low PD-L1 expression in BC, high expression of MAN1B1 is related to poor prognosis, high expression of COL6A1 in tumor cells promotes tumor growth and metastasis, and high expression of NXPH4 is associated with poor prognosis in BC." (PMID 39559360, 2024). "The evidence of FGFR3 alteration in non-tumor tissue is particularly intriguing." (PMID 38254797, 2024). "To assess the combined effects of anti-PD-1 and anti-FGFR3 small molecule inhibitors (SMI) on tumor growth and the immune response, we built an ABM that captures key facets of tumor heterogeneity and CD8+ T cell phenotypes, their spatial interactions, and their response to therapeutic pressures." (PMID 38515743, 2024). "This study concluded that basal tumours with KRT5/6, p63, and KRT14 expression had a better response to chemotherapy, while luminal tumours with active PPAR expression and activating mutations in FGFR3 showed expression of KRT20, FOXA1, and GATA3." (PMID 39594166, 2024). "Additionally, in vivo studies on FGFR3-dependent models have shown that pemigatinib significantly suppresses tumor growth." (PMID 39764422, 2024). "Results showed that FGFR3 expression was mainly detected in tumor malignant cells." (PMID 37283287, 2023). "miR-100, a downregulated miRNA in PC tissues and cell lines, could increase DDP sensitivity and suppress tumor growth in vivo via targeting fibroblast growth factor receptor 3 (FGFR3)." (PMID 37560164, 2023). "If an S1 tumor were identified before treatment, it might be possible to change its susceptibility to CPI by using an inhibitor targeting FGFR3 or KDM5B." (PMID 37105962, 2023). "Consequently, exploring the tumor microenvironment (TME) in the context of FGFR3 status emerges as a promising avenue for novel therapeutic interventions." (PMID 37980528, 2023). "Tumor cells display mainly cytosolic positivity, with rare nuclear FGFR3 staining." (PMID 38067258, 2023). "FGFR1 and FGFR3 expression was determined via IHC on the primary patient tumour, PDXs and PDXOs and very low expression of FGFR1 and FGFR3 were noted in those with high FGFR2c expression confirming that the FGF2/FGFR2c autocrine loop is the target of BGJ398 in these models." (PMID 38062117, 2023).
tumor (continued). "Altogether, these data strongly suggest that siRNA-mediated FGFR3 gene knockdown might suppress tumor metastasis by blocking the EMT machinery and relevant signaling activity in the UTUC cells." (PMID 36675289, 2023). "Our analysis of TCGA data demonstrated that increased FGFR3 expression is significantly associated with the IO score negative classification, thereby suggesting a cold tumor microenvironment." (PMID 36806983, 2023). "Erdafitinib (Balversa®®), a tyrosine kinase (TKI) FGFR1-4 inhibitor, demonstrated anti-tumor activity in preclinical models as well as a Phase I trial (NCT01703481) in patients with known somatic FGFR3 alterations for patients with mUC or intrahepatic cholangiocarcinoma." (PMID 36358849, 2022). "FGFR3 inhibition serves as a pivotal and first step in the approval of targeted therapies in urothelial cancers based on the unique molecular alterations present in an individual tumor." (PMID 36358849, 2022). "Since FGFR3 is upstream of Ras, a tumor with mutated Ras would not need FGFR3 to drive Raf/MAPK mitotic signaling to induce a hyperproliferative phenotype." (PMID 35681556, 2022). "Tumor testing revealed clinically relevant molecular alterations, including the known germline pathogenic variant STK11, a KRAS somatic pathogenic variant, and FGFR3 gene amplification." (PMID 35543335, 2022). "FGFR3-targeted therapy may be an encouraging choice for low-IRGRS tumours, especially in the LumP subtype of MIBC." (PMID 36267410, 2022). "We believe that FGFR3 is important to the biological function of tumor metastasis and could be a promising target for remodeling TME." (PMID 35991125, 2022). "Interestingly, mRNA expression of FGFR3 was slightly increased (fold change = 1.5) compared with tumor-adjacent normal tissue in this sample." (PMID 36142417, 2022). "Hematopoietic neoplasms associated with FGFR1 rearrangement are included in the family of myeloid and lymphoid neoplasms with varying responsiveness to TKIs, though other neoplasms such as AMLs, ALLs, and MPSs with FGFR3 are characterized by aggressive clinical behavior and resistance to imatinib." (PMID 36551764, 2022). "The mutation frequencies of several tumor-suppressor genes including FAT1, CDKN2A, FGFR3, and CASP8 were lower in the HPV-positive group of HNSC, and even the mutation frequencies of FAT1, CDKN2A, and CASP8 were 0, indicating that the biological processes regulated by these genes were not disrupted." (PMID 35392231, 2022). "Considering its inverse relationship with anti-tumor immune response and the relationship to the phenotype of lymphocyte exclusion, it is a reasonable to expect MHC-L tumors with low immune infiltration to be enriched by FGFR3 gene mutations." (PMID 35223828, 2022). "Only patients with both FGFR3 mutations and increased FGFR3 expression showed CR at six months (33%), whereas patients with only FGFR3 expression demonstrated no tumor response." (PMID 35992775, 2022). "Highly expressed FGFR3 in 3.3% NSCLC tumour samples (Netherlands)." (PMID 36297654, 2022). "However, in tumours of epithelial origin, FGFR3 can limit tumour growth and thus be considered a tumour suppressor." (PMID 36422592, 2022). "Of note, FGFR3 mutations are enriched in LumP tumors and we observed FGFR3 mutations not only in two LumP PDXs, including one derived from UTUC, but also in two Ba/Sq PDXs, including one derived from an SCC tumor." (PMID 36033544, 2022). "R3Mab demonstrated robust antitumor activity in FGFR3-dependent tumor cells in xenograft models." (PMID 34638374, 2021).
tumor (continued). "The model is carefully calibrated and validated with experimental measures of tumor volume with and without the FGFR3 mutation." (PMID 34984415, 2021). "Notably, the patient (P2) who received multiple EGFR TKIs likely acquired FGFR3 R248C and/or G380R to overcome the anti-tumor activity of TKIs, including osimertinib and afatinib, although pretreatment samples were unfortunately not available." (PMID 33710807, 2021). "Innerhalb der 279 HNSCC-Tumoren des The Cancer Genome Atlas konnten FGFR-Mutationen in sieben Tumoren (2,5 %) nachgewiesen werden (FGFR1-Mutation in einem HPV-negativen Tumor, FGFR2-Mutationen in zwei HPV-negativen Tumoren und FGFR3-Mutationen in je zwei HPV-negativen und -positiven Tumoren)." (PMID 32519203, 2021). "The expression level of FGFR3 transcript in this tumor was much higher than that detected in other 35 cases (about 200 times in FPKM), indicating that it may constitutively activate FGFR3 by changing its regulatory domain." (PMID 33578820, 2021). "Finally, we selected a clone that showed anti-tumor effects and FGFR3 degradation against FGFR3-overexpressing cells." (PMID 34207911, 2021). "As such, genome and transcriptome characterization offer opportunities for patient stratification; tumor mutational burden (TMB), FGFR3 activation, ERCC2 mutation, PD-L1 expression, and RNA subtyping have shown promise for clinically relevant segmentation of primary bladder cancer." (PMID 33420073, 2021). "In addition, class 3 weights were associated with FGFR3 and PIK3CA mutations, as well as lower tumor stage and grade." (PMID 33863885, 2021). "A corresponding interaction between the immune system and the response to chemotherapy could be responsible for the MMC sensitivity seen in wild-type FGFR3 tumours in the present study." (PMID 34934968, 2021). "Bei einem Patienten mit FGFR3-mutierten/fusioniertem Tumor wurde eine Komplettremission erreicht." (PMID 32519203, 2021). "Moreover, surveillance by MSA seems to be more efficient in the assessment of smoking patients with an FGFR3 wild-type tumor, which is genetically more unstable." (PMID 34884669, 2021). "FGFR3 can serve as a potential biomarker, based on the negative correlation of mutated FGFR3 and tumor malignant degree." (PMID 33407469, 2021). "Only patients with both FGFR3 mutations and increased expression of pFGFR3 showed a CR at six months (33%), whereas patients with only pFGFR3 expression did not demonstrate any tumor response." (PMID 33799514, 2021). "And the delivered miR-100 played an anti-tumor effect on GBM by regulating FGFR3 directly." (PMID 34055646, 2021). "In an attempt to identify which FGFR3-mediated effect has more impact on tumor growth, we computed the difference between the tumor volume when FGFR3 only impacts the tumor cell proliferation rate and the tumor volume when FGFR3 only impacts tumor cell survival." (PMID 34984415, 2021). "In the present case, profiling of tumor DNA identified FGFR3 amplification with 10 copies." (PMID 34765202, 2021). "In addition to mutations of FGFR3 and KDM6A, we identify ZFP36L1 as a novel, significantly mutated tumor suppressor gene." (PMID 33397444, 2021). "Furthermore, we explored the correlation between FGFR3 expression and the tumor pathological stages by the GEPIA2 approach." (PMID 34160364, 2021).